TMEM74B (transmembrane protein 74B)
Synonyms: C20orf46; FLJ11190
Tractability: Antibody: UniProt predicts a signal peptide or a membrane-spanning region. PROTAC: its protein half-life has been measured.
Gene: Protein-coding gene on chromosome 20 (1,180,561 to 1,186,842, reverse strand). Ensembl gene ENSG00000125895.
Subcellular location: Membrane
Subcellular location (Human Protein Atlas): Golgi apparatus; Nucleoplasm
Gene Ontology:
Cellular component: membrane
Genetic constraint (gnomAD): Loss-of-function variants: 11 observed, 10.53 expected, observed/expected ratio (o/e) 1.04, 90% interval 0.65 to 1.68. The upper end of that interval is the gene's LOEUF score, 1.68, which puts it in group 6 of 6, group 1 being the genes least tolerant of losing a copy. Missense variants: 342 observed, 328.73 expected, observed/expected ratio (o/e) 1.04, 90% interval 0.95 to 1.14. Synonymous variants: 151 observed, 147.65 expected, observed/expected ratio (o/e) 1.02, 90% interval 0.89 to 1.17.
Homologues: Orthologues: chimpanzee TMEM74B (99% identical), macaque TMEM74B (89% identical), pig TMEM74B (88% identical), mouse Tmem74b (82% identical), rat Tmem74b (81% identical), dog TMEM74B (51% identical), zebrafish tmem74b (48% identical), tropical clawed frog tmem74b (43% identical). Paralogues in human: TMEM74 (39% identical).
Diseases named in the same sentence as TMEM74B in open-access papers:
TMEM74B is named in the same sentence as 2 diseases in open-access papers, as found by Europe PMC text mining. Sharing a sentence is not in itself a finding about the gene and the disease. The quoted sentences say what the papers report.
tumor (1 paper, 2020). "Genes whose growth profiles most similarly match the T cell growth when stimulated by IL-2 include genes such as: TMEM74B and TTC36, a transmembrane protein and a tumor suppressor." (PMID 33105566, 2020).
TMEM74B also shares sentences with these, for which no sentence is quoted: asthma (1 paper).